MFHAS1 (multifunctional ROCO family signaling regulator 1)
Description:
Probable GTP-binding protein. Functions in innate immunity and more specifically the inflammatory response as a regulator of the Toll-like receptor TLR2 and TLR4 signaling pathways. Negatively regulates the part of the TLR4 signaling pathway that leads to the activation of the transcription factor AP-1. By retaining the phosphatase complex PP2A into the cytoplasm, prevents the dephosphorylation of the AP-1 subunit JUN which is required for proper activation of the transcription factor. Both inhibits and activates the TLR2-dependent signaling pathway. Positively regulates the TLR2 signaling pathway to activate specifically the downstream p38 and JNK MAP kinases and promote the polarization of macrophages toward the pro-inflammatory M1 phenotype. It may also play a role in the regulation of inflammation induced by high glucose through the PKB/AKT signaling pathway. Also involved in erythrocyte differentiation through activation of the ERK1/ERK2 signaling pathway.
Synonyms: MASL1; LRRC65; ROCO4
Tractability: PROTAC: UniProt records ubiquitination sites on it; ubiquitination databases record sites on it.
Gene: Protein-coding gene on chromosome 8 (8,783,354 to 8,893,630, reverse strand). Ensembl gene ENSG00000147324.
Subcellular location: Cytoplasm
Subcellular location (Human Protein Atlas): Nucleoplasm; Cytosol
Gene Ontology:
Molecular function: GTP binding; protein binding; protein phosphatase 2A binding; ubiquitin protein ligase binding
Biological process: erythrocyte differentiation; inflammatory response; innate immune response; intracellular signal transduction; negative regulation of inflammatory response; negative regulation of protein localization to nucleus; negative regulation of toll-like receptor 2 signaling pathway; negative regulation of toll-like receptor 4 signaling pathway; positive regulation of ERK1 and ERK2 cascade; positive regulation of JNK cascade; positive regulation of p38MAPK cascade; positive regulation of phosphatidylinositol 3-kinase/protein kinase B signal transduction; positive regulation of toll-like receptor 2 signaling pathway; regulation of macrophage activation; defense response; regulation of toll-like receptor signaling pathway
Cellular component: cytoplasm; cytoskeleton; lysosome; mitochondrion
Genetic constraint (gnomAD): Loss-of-function variants: 47 observed, 69.8 expected, observed/expected ratio (o/e) 0.67, 90% interval 0.53 to 0.86. The synonymous counts are far from expectation, so gnomAD's model fits this gene poorly and the ratio says little. Missense variants: 1,780 observed, 1,342.6 expected, observed/expected ratio (o/e) 1.33, 90% interval 1.27 to 1.38. Synonymous variants: 947 observed, 630.9 expected, observed/expected ratio (o/e) 1.5, 90% interval 1.42 to 1.58.
Homologues: Orthologues: chimpanzee MFHAS1 (99% identical), rabbit MFHAS1 (95% identical), macaque MFHAS1 (95% identical), rat Mfhas1 (95% identical), mouse Mfhas1 (94% identical), pig MFHAS1 (94% identical), dog MFHAS1 (93% identical), guinea pig MFHAS1 (87% identical), tropical clawed frog mfhas1 (68% identical), zebrafish mfhas1 (63% identical). Paralogues in human: SCRIB (20% identical), ERBIN (19% identical), LRRC7 (18% identical), PHLPP1 (17% identical), PHLPP2 (17% identical), PIDD1 (14% identical), LRRC1 (13% identical), LRRIQ4 (13% identical), LRRK1 (13% identical), LRRD1 (12% identical), SHOC2 (12% identical), LRRC40 (12% identical), and 19 more.
Diseases named in the same sentence as MFHAS1 in open-access papers:
MFHAS1 is named in the same sentence as 34 diseases in open-access papers, as found by Europe PMC text mining. Sharing a sentence is not in itself a finding about the gene and the disease. The quoted sentences say what the papers report.
malignant fibrous histiocytomas (6 papers, 2014 to 2019). "On top of the enhanced expression of MFHAS1 in malignant fibrous histiocytomas, the gene coding for MFHAS1 was found to be a potential oncogene for gastric, oesophageal, and gastroesophageal cancers." (PMID 30609797, 2019). "In previous studies, MFHAS1 was mostly reported as a predictor of malignant fibrous histiocytoma and gastrointestinal tumors." (PMID 31696221, 2019). "Malignant fibrous histiocytoma amplified sequence 1 (MFHAS1 or MASL1), a member of the ROCO protein family, is a predicted oncoprotein in malignant fibrous histiocytomas (MFHs), gastrointestinal tumors, and B-cell lymphoma." (PMID 27783989, 2016).
Sepsis (5 papers, 2015 to 2025). Sepsis is defined as life-threatening organ dysfunction caused by a dysregulated host response to infection. "The fine mapping of the 8p23.1 region revealed a leading genetic variant significantly associated with sepsis located within intron 1 of the MFHAS1 gene." (PMID 35345767, 2022). "Fine-mapping studies prioritized the variant rs13249564 within intron 1 of MFHAS1 gene associated with sepsis (p = 9.94 × 10−4; OR = 0.65; 95%CI = 0.50–0.84)." (PMID 35345767, 2022). "Our study shows that MFHAS1’s activity is associated with sepsis in humans and MFHAS1 levels increase during immune response." (PMID 26599367, 2015). "Until now, little was known about the relationship of MFHAS1 and sepsis, and the mechanisms underlying the effect of MFHAS1 on the TLR2 signaling pathway and inflammation." (PMID 26599367, 2015). "Studies have shown that the level of malignant fibrous histiocytoma amplified sequence 1 (MFHAS1) in sepsis patients is significantly increased, and it drives the inflammatory response by activating the TLR2/c-Jun N-terminal kinase (JNK)/NF-κB pathway." (PMID 40643532, 2025). "Taken together, this evidence supports that MFHAS1 deserves further exploration as a biological candidate gene for sepsis." (PMID 35345767, 2022). "This study aimed to examine the relationship of MFHAS1 and sepsis, and the effect of MFHAS1 on the TLR2 signaling pathway." (PMID 26599367, 2015). "Blood IL-6 and MFHAS1 concentrations were found to be significantly higher in the sepsis group than in the control group (p < 0.05)." (PMID 26599367, 2015). "Blood samples were collected from eight sepsis patients after surgery and eight patients undergoing selective surgery to determine blood MFHAS1 levels." (PMID 26599367, 2015). "Our results suggest that the role of MFHAS1 in sepsis and its potential utility in the management of this condition must be investigated further." (PMID 26599367, 2015). "Besides, MFHAS1 gene expression was specially increased in peripheral blood mononuclear cells from patients with sepsis." (PMID 35345767, 2022). "Since the expression of MFHAS1 was increased in PBMC from patients with sepsis in this article, the elevation of blood MFHAS1 may because it gets released during cell necrosis in sepsis." (PMID 26599367, 2015). "Given its dual effects on TLR2 signaling pathway and inflammation, MFHAS1 might be a suitable novel therapeutic tool to achieve immune balance in sepsis." (PMID 26599367, 2015). "Despite this, and irrespective of the fact that MFHAS1 correlates with the lead variants in the admixture mapping stage, our results do not allow us to infer whether this gene is driving the association or its causally involved in sepsis." (PMID 35345767, 2022). "Another study revealed that PJA2 contributed to MFHAS1 ubiquitylation, positively regulating TLR2-mediated JNK/p38 pathway, which stimulated M1 macrophage polarization as well as M2 to M1 macrophage transformation in sepsis." (PMID 34372882, 2021). "The aim of this present study is to investigate the relationship of MFHAS1 and sepsis, and the effects of MFHAS1 on the TLR2 signaling pathway and inflammation, and highlight this protein as an optional target in the treatment of inflammation in sepsis." (PMID 26599367, 2015). "MFHAS1 may represent one of the factors that changes in the different stages of sepsis through TLR2, although the time span of the inhibitory effect of MFHAS1 is short." (PMID 26599367, 2015). "The role of MFHAS1 in targeting TLR2 involved in sepsis has not been examined thus far." (PMID 26599367, 2015). "Further research should be focused on whether MFHAS1 has the same effect on TLR2, using other ligands like bacterial lipopeptides, and animal experiments should be performed to further verify the effect of MFHAS1 on the TLR2 signaling pathway, and its effect on inflammation and sepsis." (PMID 26599367, 2015).
B-cell lymphoma (3 papers, 2007 to 2017). "A recent NGS study of 215 B-cell lymphoma characterized 3 mutated genes: ITPKB, MFHAS1, and XPO1 present in 18 cases (39%, 28%, and 39% respectively) of PMBL." (PMID 27806315, 2017). "The probe corresponding to the Gene Hs.24724 (official symbol MFHAS1, also known as MASL1) is a candidate oncogene found in amplification of 8p23.1 and translocated in an immunoblastic B-cell lymphoma cell line." (PMID 17559667, 2007).
colorectal cancer (3 papers, 2016 to 2023). A primary or metastatic malignant neoplasm that affects the colon or rectum. "MFHAS1 is an oncogene with expression in tumor-associated macrophages that has been associated with colorectal cancer (CRC) progression." (PMID 36673024, 2023). "MFHAS1 is predicted to drive progression of colorectal cancer by integrating signals from tumor-associated macrophages, a cell type involved in the initiation, progression, and metastasis of several cancers." (PMID 34072580, 2021). "In this study, we detected a positive association between MFHAS1 expression in TAMs and human colorectal cancer (CRC) TNM stage." (PMID 27783989, 2016). "In this study, we found that MFHAS1 expression in TAMs isolated from CRC tissues was positively associated with the human colorectal cancer (CRC) TNM stage." (PMID 27783989, 2016). "The aim of this present study is to investigate the relationship of MFHAS1 in colorectal cancer (CRC) cell-induced macrophages polarization and CRC progression." (PMID 27783989, 2016).
asthma (2 papers, 2017 to 2025). "In the unadjusted model of current wheeze, the CpG site with the strong association (cg12077460) mapped to the MFHAS1 gene, whereas the top association in current asthma mapped to ZFPM1 (cg04983687)." (PMID 29046734, 2017). "Regarding MFHAS1, although it is a less characterized gene, a recent study identified MFHAS1 as a potential shared genetic locus between endometriosis and asthma, suggesting its involvement in shared immuno-inflammatory mechanisms." (PMID 40863222, 2025).
diabetes (2 papers, 2021 to 2025). "Further, MFHAS1 and IQGAP2 have some known association with diabetes or related disorders, whereas the other three genes: ZMYM3, HSD17B10 and ABCB7 have no known direct association with diabetes." (PMID 41462339, 2025).
endometriosis (2 papers, 2023 to 2025). The growth of functional endometrial tissue in anatomic sites outside the uterine body. "The accumulation of variants in MFHAS1 may indicate a contribution of immune response or cellular signaling pathways in endometriosis, a hypothesis that warrants further investigation." (PMID 40863222, 2025). "In the ovary, (a tissue commonly affected by endometriosis) the prominent involvement of MFHAS1, CLDN23, USP4, and GATA4 was identified, all of which are regulated by eQTLs." (PMID 40863222, 2025). "Although the vagina is an uncommon site for endometriosis, genes such as CLDN23, MFHAS1, and PRAG1 showed notable functional associations." (PMID 40863222, 2025). "Similarly, genes shared between endometriosis, uterine fibroids, ovarian cancer, migraine and depression (RHOA, FOXP1, ESR1, WNT4, GREB1, FSHB), and endometriosis, migraine and asthma (IGF1, SMAD3, MFHAS1), were enriched in hormone receptor signalling and inflammation pathways, respectively." (PMID 37159502, 2023).
Obesity (2 papers, 2021 to 2022). Accumulation of substantial excess body fat. "The colocalization analysis implicates genes involved in body mass index (BMI)/obesity and neuroticism (ARPP21, RP11-62H7.2, MFHAS1, RHEBL1)." (PMID 36297114, 2022).
acute lymphoblastic leukemia (1 paper, 2022). Leukemia with an acute onset, characterized by the presence of lymphoblasts in the bone marrow and the peripheral blood. "Previous studies have revealed the role of miR-19/CYLD/NFKB and miR-429/MYCN/MFHAS1 FFLs in the development or relapse of T-lineage acute lymphoblastic leukemia (T-ALL)." (PMID 35805200, 2022).
autism spectrum disorder (1 paper, 2025). A spectrum of developmental disorders that includes autism, and Asperger syndrome. "Several variants in MFHAS1 (rs2271342, rs12677543, rs12682352, rs2409091, rs9644776, rs60315134, rs59046059, rs11784052, rs35039922, rs57312668, rs4841051, rs1039916, rs3789849, rs7820146, rs3925830, rs332037, rs332039, rs332040) and SLC25A12 (rs59844139) were linked to autism spectrum disorder." (PMID 40282399, 2025).
COVID-19 (1 paper, 2022). A disease caused by infection with severe acute respiratory syndrome coronavirus 2. "On the other hand, higher methylation of PSMB9, MRPS2, MFHAS1, and MAT2B genes are known to be expressed in COVID-19 patients with high viral load or severe infection, which could translate to a lower expression of those genes." (PMID 36371196, 2022).
Encephalopathy (1 paper, 2022). Encephalopathy is a term that means brain disease, damage, or malfunction. "Interestingly, MFHAS1 has also been implicated in sepsis-associated encephalopathy and intellectual impairment." (PMID 35743705, 2022).
Hodgkins lymphoma (1 paper, 2024). A heterogeneous group of malignant lymphoid neoplasms of B-cell origin characterized histologically by the presence of Hodgkin and Reed-Sternberg (HRS) cells in the vast majority of cases. "In Hodgkin’s lymphoma, MFHAS1 had high mutation rate, which indicated a tumorigenesis role of MFHAS1." (PMID 39588389, 2024).
leiomyosarcoma (1 paper, 2023). An uncommon, aggressive malignant smooth muscle neoplasm, usually occurring in post-menopausal women. "In the leiomyosarcoma sample, the genes involved in cell growth, survival, and proliferation (MFHAS1, YAF2, SOX5, and PAK5) were also overexpressed." (PMID 36673024, 2023).
osteoarthritis (1 paper, 2022). A noninflammatory degenerative joint disease occurring chiefly in older persons, characterized by degeneration of the articular cartilage, hypertrophy of bone at the margins and changes in the synovial membrane. "Annotated genes include MFHAS1 (cg01784220 in the 1st exon), a gene involved in Toll-like receptor signaling, which is thought to be centrally involved in the osteoarthritis-related immune response in synovial joints." (PMID 35679866, 2022). "We identified methylation sites that play a putative causal role in osteoarthritis, for example for the WWP2, BSN, and MFHAS1 genes." (PMID 35679866, 2022).
renal fibrosis (1 paper, 2019). A final common manifestation of a wide variety of chronic kidney diseases characterized by glomerulosclerosis and tubulointerstitial fibrosis. "However, the functions of MFHAS1 on inflammation and renal fibrosis in DN are not understood." (PMID 31696221, 2019).
schizophrenia (1 paper, 2019). A major psychotic disorder characterized by abnormalities in the perception or expression of reality. "Several other genes in this region show suggestive evidence of differential expression/splicing in ASD, including MSRA, which has been previously associated with schizophrenia, MFHAS1, and PINX1." (PMID 31230729, 2019).
soft tissue tumor (1 paper, 2023). "Multifunctional ROCO family signaling regulator 1 (MFHAS1) is linked to soft tissue tumor and cell cycle." (PMID 36624383, 2023).
cancer (8 papers, 2014 to 2025). A tumor composed of atypical neoplastic, often pleomorphic cells that invade other tissues. "Previous studies on MFHAS1 were mostly reported in cancer-related and inflammation-related researches." (PMID 31696221, 2019). "This chromosomic region harbours the CSMD1, AGPAT5, TUSC3, DLC1, CLDN23, and MFHAS1 cancer-related genes." (PMID 30185896, 2018). "MFHAS1, regulated by TF MYCN in our remission sub-network, may be a significant prognosis factor for AML in The Cancer Genome Atlas (TCGA) cohort and could promote the progress of cancer." (PMID 30195757, 2018).
tumor (6 papers, 2015 to 2025). "First, we determined the MFHAS1 mRNA levels in CRC tumor tissues and tumor adjacent tissues isolated from human CRC tumors samples of TNM stage I (n = 8), II (n = 13), III (n = 10), and IV (n = 7) using qRT-PCR." (PMID 27783989, 2016). "Thus, we speculate that PJA2 overexpression in vivo may contribute to tumor progression by affecting MFHAS1 expression and function." (PMID 34072580, 2021). "Since the functions and activation states of TAMs are often shaped by the tumor microenvironment including tumor cells, we speculated that the high MFHAS1 expression in TAMs of high-grade CRC tumors might be attributed to prolonged interaction with tumor cells." (PMID 27783989, 2016). "MFHAS1 knockdown in macrophages reduced M2 polarization and inhibited CRC cell growth, migration, and EMT in vitro and tumor formation in vivo." (PMID 27783989, 2016). "To explore the functional significance of this tumor cell-induced MFHAS1 expression, we established RAW264.7 macrophages stably transfected with an MFHAS1-targeting shRNA (shMFHAS1) or a scrambled shRNA (shNC)." (PMID 27783989, 2016). "Genes such as GATA4, CLDN23, MICB, MFHAS1, and BMPR2 were enriched in multiple signatures including estrogen response, coagulation, DNA repair, tumor-promoting inflammation, immune evasion, angiogenesis, sustained proliferative signaling, resistance to cell death, and metastasis." (PMID 40863222, 2025). "Similarly, we determined the MFHAS1 mRNA and protein levels in TAMs isolated from human CRC tumor tissues." (PMID 27783989, 2016).
MFHAS1 also shares sentences with these, for which no sentence is quoted: infection (3 papers); cardiovascular disease (2); gastrointestinal tumors (2); coronary artery disease (1); diabetic nephropathy (1); glioma (1); heart disease (1); Hypertension (1); Insulin resistance (1); intellectual impairment (1); migraine (1); Tinnitus (1); type 1 diabetes mellitus (1); type 2 diabetes mellitus (1).